EGFR (epidermal growth factor receptor)
Diseases named in the same sentence as EGFR in open-access papers (continued):
Sharing a sentence is not in itself a finding about the gene and the disease.
lung cancer (continued). "We also tested a patient-derived xenograft model of EGFR mutant lung cancer (MGH134-1) and again observed the greatest antitumor effects from the combination treatment of osimertinib with an anti-CD47 antibody." (PMID 38483480, 2024). "We treated a patient with choroidal metastasis of EGFR-mutant lung cancer during gefitinib treatment." (PMID 38962043, 2024). "In this regard, inhibiting CD109 is known to reduce EGFR signaling, suppress the Akt/mTOR pathway, and increase tumor cell sensitivity to EGFR inhibitors, highlighting its potential as a promising therapeutic target in lung cancer." (PMID 39990858, 2024). "All these studies highlighted the role of EGFR in the transition of lung cancer from preinvasive to invasive status." (PMID 38496837, 2024). "EGFR-TKIs exhibit a robust inhibitory effect on EGFR mutant lung cancer cells; however, their inhibitory activity against wild-type lung cancer cells is comparatively weaker." (PMID 38649732, 2024). "Lung cancer development and progression are influenced by the transmembrane protein EGFR, which has cytoplasmic kinase activity." (PMID 38773634, 2024). "Taken together, our results highlight that the exosome-based EGFR targeting siRNA delivering system is a promising therapeutic strategy for BM of lung cancer." (PMID 38589859, 2024). "One study has shown that administering afatinib and paclitaxel to NSCLC cells resistant to EGFR TKIs using a pulmonary microsphere system led to effective treatment of drug-resistant lung cancer." (PMID 38474400, 2024). "Although the clinical success of TKIs has been dramatic, specifically for the first/second/third EGFR inhibitors, most lung cancer patients finally encounter disease progression because of various TKI resistance mechanisms." (PMID 38827327, 2024). "Although the precise mechanism by which CBX3 contributes to lung cancer is far from being completely elucidated, some evidence points to its potential interaction with EGFR signaling." (PMID 39272883, 2024). "DUSP22 deletion in lung cancer cells increases dependence on EGFR activity for growth and survival, as it leads to co-activation of EGFR and ERK1/2." (PMID 38877005, 2024). "HER2 amplification is considered one of the oncogenic driving factors of lung cancer and an important mechanism of EGFR-independent mechanisms of acquired resistance to EGFR-TKIs." (PMID 39184039, 2024). "In this study, we found that TrxR1 inhibitors can significantly enhance the toxicity of VEGFR and EGFR inhibitors in lung cancer cells." (PMID 38164168, 2024). "The advent of targeted therapies began with EGFR-targeted treatments for lung cancer and changed the outlook for lung cancer dramatically." (PMID 39272844, 2024). "EGFR is overexpressed in glioblastoma, breast, and lung cancers leading to dysregulation of the EGFR pathway and increased cell proliferation." (PMID 39139449, 2024). "Osimertinib is a third-generation EGFR-TKL that selectively and significantly suppresses T790M-resistance mutations in lung cancer patients and is approved in the first-line treatment of EGFR-mutant lung cancer." (PMID 38234663, 2024). "The upregulation of ACSL5 in the two lung cancer cell lines harboring EGFR mutations indicates a potential link between ACSL5 overexpression and EGFR mutations." (PMID 38539505, 2024). "In the context of lung cancer, EGFR, ALK, KRAS, BRAF, Bcl-xl, SHP2 and FAK, E3 ligase ligands, are potential oncogenic targets of PROTACS." (PMID 39456995, 2024). "In lung cancer, FUT8 was identified as capable of regulating the cancer-promoting potential of cancer-associated fibroblasts through the modification of EGFR core fucosylation." (PMID 38277230, 2024). "The CEA‐positivity rate was 49% for ALK‐positive lung cancers and 73% for EGFR‐positive lung cancers, which was significantly different (p < 0.001)." (PMID 38400801, 2024).
lung cancer (continued). "To confirm the link between DUSP22-induced growth inhibition and EGFR in lung cancer cells, we assessed the colony-forming capacity of EGFRlow H520 and TC-1 cancer cells in the presence or absence of DUSP22 expression." (PMID 38877005, 2024). "This path of personalized medicine, using drugs targeting epidermal growth factor receptor (EGFR) mutations and anaplastic lymphoma kinase (ALK) rearrangements, has been shown to be successful by increasing the survival of patients with lung cancer." (PMID 38785753, 2024). "According to the study, miR-21-3p and miR-21-5p levels were elevated in EGFR-mutant lung cancer cells tolerant to EGFR-TKI treatment." (PMID 39324002, 2024). "This study provides a theoretical basis for the therapeutic intervention of PTK2 targeting EGFR- or TLRs-induced lung cancer progression." (PMID 38816856, 2024). "Our findings provide novel mechanistic insights into squamous transition and therapeutic strategy to overcome EGFR TKI resistance in lung cancer." (PMID 39687207, 2024). "ST analysis of specimens from transgenic mice with EGFR-driven lung cancer indicates spatial heterogeneity of tumors and corroborates scRNA-seq findings." (PMID 39122703, 2024). "In conclusion, our study showed that one twentieth of lung cancer patients diagnosed in Germany in 2016 received at least one EGFR, ALK, or BRAF inhibitor during follow‐up." (PMID 39693368, 2024). "Next, we compared the screening analysis to patient-observed somatic EGFR variants found in GENIE, focusing first on glioblastoma and lung cancers as those cancers commonly harbor EGFR mutations." (PMID 38548752, 2024). "Specifically, the elevated levels of ABCB1 compromise the efficacy of drugs, such as DOX, EGFR tyrosine kinase inhibitors, and cisplatin in lung cancer." (PMID 39507258, 2024). "Since the abnormal activation of the EGFR signaling pathway is one of the hallmarks of lung cancer, we took the EGFR signaling pathway as the focus of further research." (PMID 38376003, 2024). "Having used our molecular analysis to distinguish independent primary tumors from metastatic recurrences in the setting of familial EGFR-mutant lung cancer, we turned to a separate cohort of ten apparently sporadic cases with multiple EGFR-mutant lesions." (PMID 39406916, 2024). "It concluded that lung cancer coexisting with TB patients had a poor response to EGFR-TKI treatment." (PMID 39868375, 2024). "In an attempt to construct an innovative in vitro model, EGFR-mutant lung cancer organoids were established using HCC827 and H1975 cells, which are known to carry EGFR mutations." (PMID 39766891, 2024). "Fluorescence microscopy analysis indicated that the EGFR aptamer-functionalized nanoparticles effectively targeted lung cancer cells (A549 and NCI-H226) over normal lung cells (Beas2B)." (PMID 38675202, 2024). "EGFR- or ALK-altered lung cancers and BRAF mutant melanoma are some success stories of personalized cancer treatments." (PMID 38485987, 2024). "The current understanding of the roles of EREG in lung tumorigenesis and therapeutic resistance accentuates the therapeutic potential of targeting the EREG/EGFR pathway in lung cancer." (PMID 38398101, 2024). "Recent studies have delved into its mechanism of action, particularly in the context of EGFR-TKI-resistant lung cancer." (PMID 39104501, 2024). "While BRAF alterations are predominant mechanisms of resistance to EGFR therapy, we recently identified that ARAF amplification causes resistance to EGFR inhibitors in EGFR mutant lung cancer." (PMID 39456595, 2024). "In one study, Met was shown to improve the survival of lung cancer patients with type 2 diabetes mellitus (T2DM) undergoing EGFR‐TKI therapy." (PMID 38562019, 2024). "We found that genes in the Hippo pathway were the most recurrent and strongest resistance drivers to osimertinib in EGFR mutant lung cancer." (PMID 38658677, 2024).
lung cancer (continued). "Firstly, it is crucial to thoroughly gather family history, especially of lung cancer, and perform EGFR and other germline gene tests for those patients who have a familial history." (PMID 39160638, 2024). "It has been recently shown that both wild-type and catalytically inactive mutants of JMJD5 cooperate with E3 ligase HUWE1 to destabilize EGFR and EGFR tyrosine kinase inhibitor-resistant mutants for proteasomal degradation in lung cancer cells." (PMID 39000010, 2024). "Epidermal growth factor tyrosine kinase inhibitors (EGFR TKIs) exhibit remarkable clinical efficacy in advanced lung cancer." (PMID 38595915, 2024). "The role of the cell membrane-bound receptor known as the epidermal growth factor receptor (EGFR) in the development of lung cancer has been extensively studied." (PMID 39234608, 2024). "RYBP inhibits the progression and metastasis of lung cancer, suppressing the epidermal growth factor receptor (EGFR) signaling and the epithelial–mesenchymal transition (EMT)." (PMID 38785968, 2024). "Concurrent EGFR mutation and SMARCA4 deficiency in NSCLC present a complex scenario in lung cancer pathogenesis." (PMID 39465834, 2024). "Exogenous DUSP22 expression reduces the colony-forming capacity of lung cancer cells and inhibits xenograft tumor growth primarily by targeting EGFR and suppressing its activity through dephosphorylation." (PMID 38877005, 2024). "Human epidermal growth factor receptor (EGFR) is a cancer biomarker that is overexpressed in several cancers, for example, non‐small cell lung cancer, but also exhibits relatively high expression in other healthy tissues, such as skin and liver." (PMID 39403960, 2024). "Only two cases of primary lung cancer with GI metastases harboring EGFR exon 19 deletion have been reported, both of which were squamous cell carcinomas, and one responded transiently to erlotinib." (PMID 38957515, 2024). "Here, I suggest that while first-line osimertinib extends median progression-free survival (PFS) in EGFR-mutant lung cancer compared to first-generation TKIs, it reduces individual PFS in 15–20% of patients compared to first-generation TKIs." (PMID 38497774, 2024). "Agents targeting the epidermal growth factor receptor (EGFR) have been instrumental pioneers in the field of precision medicine for lung cancer." (PMID 39061010, 2024). "In another study involving 25 Asian individuals with EGFR‐TKI‐sensitive advanced lung cancer, the early administration of thoracic radiotherapy combined with targeted therapy substantially prolonged the drug resistance onset time." (PMID 38659399, 2024). "In this study, we established an EGFR-independent, erlotinib-resistant (ER) phenotype in lung cancer A549 cells by exposing them to erlotinib for an extended period." (PMID 39897079, 2024). "According to the TGCA database, about 14%, 11%, and 9% of lung cancer possess mutations in Kelch Like ECH Associated Protein 1 (KEAP1), Neurofibromatosis type 1 (NF1), and Epidermal growth factor receptor (EGFR), respectively." (PMID 39596025, 2024). "Targeting S100A9-ALDH1A1-retinoic acid signaling can retract brain relapse in EGFR-mutant lung cancer." (PMID 38953895, 2024). "Intriguingly, the morphological differences between the two EGFR-mutant lung cancer cell lines, HCC827 and H1975, remained insignificant within the organoid context." (PMID 39766891, 2024). "P00533 (epidermal growth factor receptor, EGFR), a human TMP with the Pkinase_Tyri family, is not only the hub of the POSI but also linked to lung cancer." (PMID 38658824, 2024). "Emerging evidence supports that EGFR amplification predicts worse outcomes in patients with lung cancer." (PMID 39054543, 2024).
lung cancer (continued). "A recent study shows that mGluR1 directly interacts with and stabilizes the EGFR in a glutamate-dependent manner in lung cancer brain metastasis." (PMID 39769452, 2024). "Despite targeted therapies like epidermal growth factor receptor tyrosine kinase inhibitors (EGFR-TKIs), non–small cell lung cancer (NSCLC) remains a clinical challenge due to drug resistance hampering their efficacy." (PMID 39321294, 2024). "Driver genes such as EGFR (Epidermal Growth Factor Receptor) have a significant role in the development and progression of lung cancer." (PMID 39273095, 2024). "For instance, chemotherapy combined with an EGFR inhibitor has been widely used to treat non‐small cell lung cancer; likewise, regorafenib has shown favorable effects in the combination therapy of metastatic colorectal cancer." (PMID 39618078, 2024). "Collectively, our data support a role for DUSP22 in the suppression of tumor development in lung cancer cells through the dephosphorylation of key target kinases in the EGFR signaling pathway." (PMID 38877005, 2024). "The anti-migration and anti-invasion activities of shikonin present through c-Met inhibition in EGFR mutated and highly c-Met expressive HCC827 lung cancer cells." (PMID 38203787, 2024). "Latest studies have demonstrated that targeting the ATP binding pocket of EGFR with the small molecule can be a hopeful new strategy in lung cancer treatment." (PMID 38234663, 2024). "Epidermal growth factor receptor (EGFR), which is found in approximately 40% to 50% of cancer cells, including those in lung cancer, plays a crucial role in signaling pathways related to the metastasis, growth, and angiogenesis of cancer cells." (PMID 39128942, 2024). "ALK‐ and EGFR‐positive lung cancers are predominantly adenocarcinomas, but there are differences in pathological subtypes." (PMID 38400801, 2024). "An anti-EGFR bispecific antibody is used to specifically target lung cancer cells that express EGFR." (PMID 38726321, 2024). "The treatment for MET-driven lung cancer is less developed, but the insights gained from EGFR-driven cancer can be beneficial." (PMID 38497774, 2024). "Overall, based on our in vivo and patient data, we suggest a clinical pathway incorporating phospho-MET IHC staining in addition to standard MET FISH assays to guide treatment for patients with osimertinib-resistant EGFR-mutant lung cancer." (PMID 38276867, 2024). "For example, simultaneous low-dose application of RAF, MEK, and ERK inhibitors decreased the selective pressure of each compound and overcame acquired EGFR resistance in lung cancer." (PMID 39286984, 2024). "Several studies reported the presence of both EML4-ALK and EGFR rearrangements in patients with lung cancer." (PMID 39695132, 2024). "Despite initial high response rates to first-line EGFR TKI, all non–small-cell lung cancer (NSCLC) with EGFR-activating mutation will ultimately develop resistance to treatment." (PMID 39353739, 2024). "EGFR, a transmembrane protein with tyrosine kinase activity, is ubiquitously expressed in various cells and aberrantly activated in lung cancer, colorectal cancer, and other diseases." (PMID 39102432, 2024). "Knockdown of DUSP22 using shRNA enhances EGFR dependency in HCC827 lung cancer cells and increases sensitivity to gefitinib, an EGFR inhibitor." (PMID 38877005, 2024). "In lung cancer, PDOs have shown clinical correlations when tested in response to olaparib, anti-EGFR targeted therapy, and different chemotherapeutic agents." (PMID 39358778, 2024).
lung cancer (continued). "To investigate the causal relationship between EGFR mutations and TGF-β expression, we constructed mouse LLC and SJT1601 lung cancer cell lines overexpressing human EGFRΔ19, EGFR20ins, or WT proteins using lentiviral vectors." (PMID 39004699, 2024). "First, human lung cancer EGFR-TKI resistant cell lines were generated by increasing concentrations of EGFR-TKI in the culture of PC9 and HCC827 cells in vitro, both harboring EGFRΔ19 mutations." (PMID 39004699, 2024). "Related studies have found that knocking down the HE4 gene in lung cancer can lead to inactivation and downregulation of EGFR expression, thereby inhibiting EGFR downstream signaling pathways and the growth and metastasis of lung cancer cells." (PMID 38742362, 2024). "The median time between lung cancer diagnosis and first dispensation of an EGFR inhibitor was 3.3 months." (PMID 39693368, 2024). "More real‐world data are needed to evaluate its efficacy and safety in treating locally advanced and metastatic non‐small cell lung cancer (NSCLC) following prior EGFR TKI treatment." (PMID 38798190, 2024). "In the case of the lung cancer drug ramucirumab, for example, the FDA cautions that patients treated with this drug must be those with epidermal growth factor receptor (EGFR) and ALK receptor tyrosine kinase (ALK) mutations." (PMID 38674402, 2024). "Current evidence suggests that ICI therapy for EGFR-positive lung cancer remains inadequate, probably due to the EGFR-specific TME." (PMID 39280252, 2024). "This mutation prompted the development and application of third-generation EGFR inhibitors, osimertinib and rositinib (rociletinib), to the clinical treatment of patients with drug-resistant lung cancer." (PMID 38827327, 2024). "Next, we examined the impact of these clinical factors on the OS of patients with EGFR-mutant lung cancer." (PMID 38347279, 2024). "The results of the Kaplan-Meier analysis for lung cancer patients based on their epidermal growth factor receptor (EGFR) status." (PMID 39850198, 2024). "This study represents one of the most comprehensive functional genomics studies of drug resistance in EGFR mutant lung cancer in both the 1st and 2nd line treatment settings." (PMID 38658677, 2024). "Precision therapy for lung cancer often targets EGFR, although limited evidence exists regarding the involvement of EGFR germline mutations in MPLC." (PMID 39389944, 2024). "A higher proportion of patients with ALK‐positive lung cancer were CYFRA21‐1 positive and had higher CYFRA21‐1:CEA ratios compared with EGFR‐positive lung cancer patients." (PMID 38400801, 2024). "Though we used 3 lung cancer cell lines with the same endogenous EGFR Exon 19 deletion, we observed varying levels of functionality in our assays." (PMID 38548752, 2024). "Gefitinib is an inhibitor of the epidermal growth factor receptor (EGFR), which is used to treat lung cancer." (PMID 39398192, 2024). "Recent researches have revealed that ANO1 overexpression promotes the progression of lung cancer, head and neck squamous cell carcinoma, and breast cancer through the epidermal growth factor receptor signaling pathway." (PMID 38352864, 2024). "It has been reported that an EGFR inhibitor, gefitinib, inhibits the function of P-gp in multidrug-resistant lung cancer and breast cancer." (PMID 38202856, 2024). "For example, exosomes released by lung cancer cells show an elevated level of epidermal growth factor receptor (EGFR)." (PMID 39062506, 2024). "Overall, circRNAs plays a crucial regulatory role in the occurrence, development, chemotherapy resistance, and EGFR-TKIs resistance of lung cancer." (PMID 38715012, 2024). "A total of 401 patients with EGFR-mutant non–small cell lung cancer (NSCLC) beginning treatment with EGFR TKIs from September 1, 2019, to July 31, 2022, were retrospectively analyzed." (PMID 39636639, 2024).